RNU6-729P (RNA, U6 small nuclear 729, pseudogene)
Gene: Small nuclear RNA gene on chromosome 8 (10,476,223 to 10,476,329, forward strand). Ensembl gene ENSG00000207128.
Homologues: Orthologues: chimpanzee U6 (98% identical), rabbit U6 (90% identical), macaque U6 (87% identical), mouse Gm25137 (87% identical), pig U6 (86% identical), pig U6 (83% identical), rat U6 (81% identical), pig U6 (80% identical). Paralogues in human: RNU6-1 (90% identical), RNU6-15P (90% identical), RNU6-2 (90% identical), RNU6-3P (90% identical), RNU6-4P (90% identical), RNU6-5P (90% identical), RNU6-6P (90% identical), RNU6-9 (90% identical), RNU6-12P (89% identical), RNU6-13P (89% identical), RNU6-17P (89% identical), RNU6-18P (89% identical), and 1287 more.